RNU6-359P (RNA, U6 small nuclear 359, pseudogene)
Gene: Small nuclear RNA gene on chromosome 16 (68,017,710 to 68,017,817, reverse strand). Ensembl gene ENSG00000202336.
Homologues: Orthologues: chimpanzee U6 (100% identical), macaque U6 (93% identical), rat U6 (87% identical). Paralogues in human: RNU6-842P (90% identical), RNU6-12P (89% identical), RNU6-13P (89% identical), RNU6-25P (89% identical), RNU6-29P (89% identical), RNU6-32P (89% identical), RNU6-33P (89% identical), RNU6-41P (89% identical), RNU6-1 (88% identical), RNU6-1011P (88% identical), RNU6-17P (88% identical), RNU6-18P (88% identical), and 1287 more.